EGFR (epidermal growth factor receptor)
Diseases named in the same sentence as EGFR in open-access papers (continued):
Sharing a sentence is not in itself a finding about the gene and the disease.
tumor (continued). "To study how EGFR-low and EGFR-high cells directly interact with fibroblasts, we isolated CAFs from a patient tumor and studied the cell-cell interactions utilizing the microfluidic device." (PMID 39747003, 2025). "This aberrant signaling contributes to tumor progression and metastatic dissemination, while also driving resistance to anti-EGFR therapies." (PMID 41228231, 2025). "In contrast, some reports indicate that HER4 expression can promote CRC progression under certain conditions, especially in tumours co-expressing HER2 or EGFR." (PMID 40940907, 2025). "The focus of this study was to generate potent NKCEs that bridge NKp30 on NK cells with EGFR or HER2 on tumor cells." (PMID 39811682, 2025). "It inhibits SHP2-dependent Ras/ERK signaling downstream of EGFR and prevents tumor cell invasion by downregulating Src signaling and phosphorylation of key molecules such as paxillin and Src." (PMID 40699708, 2025). "Since 72 h, tumor increment was surveyed in HT-29 cells treated by hAMSCs through the EGFR/c-Src/IRSp53/p-AKT/p-Stat3/cyclin D1 signaling cascade." (PMID 41200137, 2025). "As a recombinant anti-EGFR/CD3 bispecific antibody developed by Zhejiang Shimai Pharmaceutical Co., Ltd., SMET12 directs T cell activation to kill EGFR-positive tumor cells through binding to EGFR on tumor cell surface and CD3 receptor on T cell surface." (PMID 41583476, 2025). "Bind to specific tumor-associated antigens (e.g., EGFR, MUC-1) to inhibit tumor growth or enhance immune response." (PMID 40881676, 2025). "Mitogen-inducible gene 6 (MIG6) is encoded by the gene, ERRFI1, with its function being a well-characterized epidermal growth factor receptor (EGFR) inhibitor and tumor suppressor." (PMID 40378957, 2025). "Currently, targeted therapy against EGFR is the key to tumor treatment, and the development of various EGFR inhibitors such as gefitinib and erlotinib in the past has significantly changed the therapeutic strategy of many cancers." (PMID 40672756, 2025). "ANXA6 mediates cholesterol transport and participates in endocytosis and exocytosis and can serve as a tumor suppressor due to its ability to negatively regulate EGFR phosphorylation." (PMID 40188944, 2025). "The latest one has been shown to successfully engage and redirect NK cells to elicit tumor cell lysis of epidermal growth factor receptor-positive (EGFR+) cells in multiple studies." (PMID 39811682, 2025). "Tumor exosomes can also deliver epidermal growth factor receptor (EGFR) to host macrophages, inhibiting the production of type I interferons and thereby reducing the overall immune response in cancer patients." (PMID 40176898, 2025). "The quinazoline core, as an advantageous structural framework for drug development, is widely used in the research of anti-tumor drugs, among which the research on epidermal growth factor receptor (EGFR) tyrosine kinase inhibitors (TKIs) is the most active." (PMID 41614821, 2025). "Zalimumab is a monoclonal antibody against EGFR that effectively inhibits tumor growth by blocking EGFR signaling in preclinical models." (PMID 39910672, 2025). "The perioperative setting has been only partially explored for patients with EGFR-mutant or ALK-rearranged tumours." (PMID 40628491, 2025). "In this study, we combined image encryption with radiomics to develop a noninvasive preoperative model for predicting the response to treatment with EGFR-TKIs and ICIs based on radiomic features from three tumor regions and clinical factors." (PMID 39833943, 2025). "Due to limited tumor tissue availability, baseline EGFR, CD47, and PD-L1 expression were uninformative." (PMID 41171165, 2025). "For example, if bulk gene expression from a biopsy already tells us a tumor is EGFR-positive, do we need single-cell data to guide therapy?" (PMID 41393100, 2025).
tumor (continued). "The Wilcoxon rank sum test demonstrated significantly lower expression levels of JUN and EGFR in tumor samples compared to normal tissues, a finding further validated by paired sample comparisons." (PMID 41246859, 2025). "In tumor cells, the overexpression of EGFR has been shown to be closely related to the malignancy, metastasis, and angiogenesis, thus making EGFR a promising binding target for MRI contrast agents." (PMID 41325799, 2025). "Bypass signaling activation involves the upregulation of alternative pathways, such as MET, HER2, and RAS-MAPK, which allow tumor cells to sustain proliferation despite EGFR inhibition." (PMID 40076686, 2025). "Combination treatment with c-Met inhibitors increases the efficacy of EGFR-TKIs, thereby inhibiting tumor cell growth and proliferation and delaying relapse in drug-resistant tumors." (PMID 41346633, 2025). "The patient suffering from metastatic NSCLC had an epidermal growth factor receptor (EGFR)-mutant tumor." (PMID 40264106, 2025). "This was particularly highlighted in the context of a monomeric anti-EGFR Nanofitin showing a strong and homogeneous distribution within the tumor, with a labeling of nearly all the cancer cells as fast as 90 min post-injection." (PMID 40305184, 2025). "Sustained increases in and high levels of EGFR phosphorylation were detected in some hypoxic tumor cell lines, while EGFR phosphorylation remained low in others." (PMID 40940319, 2025). "Metformin stabilizes GM1-rich lipid rafts in TNBC, modulating EGFR signaling pathways that drive tumor proliferation and survival." (PMID 40277915, 2025). "Exosomes from EGFR-mutant NSCLC carry tumor-related RNA, contributing to EGFR-TKI resistance through signaling pathways." (PMID 40002883, 2025). "EGFR inhibitors increase tumour control by sensitising it to radiation, inhibiting DNA repair and potentially destroying cancer cells." (PMID 41228322, 2025). "Non–class 1 mutations associate with better prognosis, microsatellite stability, distal tumor location, and better anti-EGFR response." (PMID 39751654, 2025). "Overactivation of ERK and Akt, frequently triggered by p-EGFR, contributes to aggressive tumor phenotypes and therapy resistance." (PMID 41154639, 2025). "Paradoxically, however, CD109 is upregulated in SCC and we and others found that it strongly promotes SCC tumor progression via EGFR pathway activation." (PMID 40317079, 2025). "By calculating the remaining tumor cells, we found that EGFR-BBζ + CD2 CAR-T cells exhibited increased overall cytotoxic efficacy against the entire cell population in this mixed model." (PMID 40615696, 2025). "Tumor cells upregulate the PD-L1 receptor through an elaborate route that includes DNA damage signaling, IFNγ signaling, and the EGFR pathway." (PMID 39851804, 2025). "Regarding tumor markers, although some studies have reported that elevated CEA levels are associated with a higher EGFR mutation rate, its independence as a risk factor remains controversial." (PMID 41378298, 2025). "Experimental data have shown that CBD can inhibit EGF-induced EGFR-TK activity, leading to the suppression of tumor cell growth and the induction of apoptosis in vitro and in vivo." (PMID 40864738, 2025). "After tumor progression with EGFR TKI therapy and PBC in patients with EGFRm NSCLC, HER3‐DXd once every 3 weeks demonstrated clinically meaningful efficacy with durable responses, including in CNS metastases." (PMID 39712454, 2025). "Advancements in radiotherapy have contributed to new treatment strategies for EGFR-mutated NSCLC with Oligo-PD owing to the availability of stereotactic radiotherapy (SRT), an advanced radiotherapy modality with high local tumor control rates." (PMID 40647500, 2025). "Dysregulation of the EGF/EGFR signaling pathway has been shown to contribute to tumor initiation and progression." (PMID 39759123, 2025).
tumor (continued). "Targeting IGF2BP2 effectively overcomes anti-EGFR-resistance mediated by either intracellular PI3K/AKT signaling hyperactivation or CAF-mediated tumor microenvironment interactions." (PMID 40362183, 2025). "Gefitinib, a representative first-generation EGFR-TKI, inhibits tumor growth and metastasis by suppressing EGFR activity, thereby promoting tumor cell apoptosis." (PMID 39754146, 2025). "In conclusion, these data from animal studies suggests that STARD4 knockdown suppresses tumorigenesis and enhances the anti-tumor effect of lenvatinib in vivo by inhibiting EGFR/PI3K/AKT signaling pathway." (PMID 40831538, 2025). "Anti-EGFR therapies, such as EGFR tyrosine kinase inhibitors cetuximab and panitumumab, block or slow down the growth of tumor cells." (PMID 40076613, 2025). "EGFR promotes vascular endothelial cell proliferation, endowing tumor tissues with abundant blood supply and facilitating rapid tumor cell proliferation." (PMID 41244899, 2025). "This review explores the evolving landscape of utilizing liquid biopsies, specifically circulating tumor DNA (ctDNA), in the management of NSCLC with EGFR mutations." (PMID 38473302, 2024). "In the fetal tumor cluster, we observed expression of epidermal growth factor receptor (EGFR), also present in normal hepatocytes and cholangiocytes." (PMID 39567475, 2024). "The synergistic application of EGFR and mTOR inhibitors has been shown to significantly enhance the anti-tumor efficacy of these drugs." (PMID 38751788, 2024). "Single-cell analysis suggested EGFR and MUC1 together had better tumor specificity than the combination of EGFR with other drug targets." (PMID 39664199, 2024). "Although epithelial cells originally express of EGFR, the expression level are much lower than tumor tissue." (PMID 38888415, 2024). "This approach facilitates the direct targeting of EGFRvIII-positive tumor cells while also recruiting bystander T cells to attack EGFR-positive but EGFRvIII-negative tumor cells, thereby overcoming antigen heterogeneity and reducing toxicity to normal tissues." (PMID 39506843, 2024). "EGFR-mutant NSCLCs have become a paradigm to study tumor response to drug treatments, leading to significant improvements in clinical outcomes." (PMID 38546390, 2024). "ISCs can develop into tumor stem cells when their signaling pathways involved in proliferation control, such as the EGFR signaling pathway, are affected." (PMID 37962464, 2024). "EGFR, a tyrosine kinase receptor, is a crucial component of fundamental signaling pathways in the cell and plays a pivotal role in tumor progression." (PMID 39451251, 2024). "EGFRvIII is a splice variant of EGFR caused by an in-frame deletion of exons 2–7 that is tightly restricted to GBM, though shows significant intra-tumor heterogeneity." (PMID 39606234, 2024). "To find an optimal TAA target to combine with EGFR, we constructed a computational pipeline which integrated multiple single-cell RNA sequencing datasets of both tumor and normal tissues from public sources." (PMID 39664199, 2024). "Since EGFR-mediated signal transduction stimulates tumour cell proliferation, local invasion, angiogenesis, and metastasis, it has been linked to a number of human malignancies." (PMID 39443462, 2024). "In vitro and in vivo experiments validated that CXCR1+ neutrophils resulted in resistance to third-generation EGFR-TKI via activating TNF-α/NF-κB signaling pathway in tumor cells." (PMID 39638994, 2024). "It has also been shown that co-targeting COX2 with BRAF + EGFR durably inhibits tumor growth capacity in patient-derived tumor xenograft models." (PMID 38717677, 2024). "We recently developed an original immunocytology and glass slide-based circulating tumor cell (CTC) detection platform for both CTC enumeration and EGFR mutation analysis with DNA extracted from CTCs." (PMID 39335743, 2024).
tumor (continued). "The second cluster was significantly associated with several tumor signaling pathways, such as the PI3K-Akt signaling pathway, EGFR tyrosine kinase inhibitor resistance pathway, Ras signaling pathway, and MAPK signaling pathway." (PMID 38166892, 2024). "The discovery of EGFR tyrosine kinase inhibitor (EGFR‐TKI) is an important milestone in the development of tumor‐targeted therapy in NSCLC and greatly improves the outcomes of NSCLC patients." (PMID 39406371, 2024). "We found that both EGFR gene mutation and TKI treatment of tumor cells carrying EGFR mutations have little effect on the intracellular level of Rab27a." (PMID 39062533, 2024). "For advanced-stage patients with EGFR wild type tumours at diagnosis, treatment patterns were generally heterogeneous across all lines of therapy." (PMID 38668049, 2024). "Anti-EGFR agents are well known for their ability to induce early tumor shrinkage, and anti-EGFR agent monotherapy is reported to be feasible even for frail patients." (PMID 38233703, 2024). "Both agents were found to slow tumor growth as a single agent but had increased efficacy in combination with the EGFR blocking antibody." (PMID 39239273, 2024). "Abnormal EGFR expression is found in over 70% of malignant tumors, such as bladder, lung, and prostate cancers, making it an ideal target for tumor diagnosis and treatment." (PMID 39451714, 2024). "The new knowledge generated is the computed score for CD44, EGFR, E-cadherin, and vimentin, which can be used as indicators to predict tumor aggressiveness by implicating recurrence." (PMID 39050298, 2024). "Driver mutations, like the mutation of the epidermal growth factor receptor (EGFR) gene, prevalent in 48% of Asian and 19% of Western LUAD patients, play a crucial role in tumor growth and invasiveness." (PMID 38540317, 2024). "HER3 is a member of the epidermal growth factor receptor (EGFR) family (EGFR, HER2, HER3 and HER4) and has been implicated in tumor initiation, progression and resistance, a major contributor to treatment failure." (PMID 38951909, 2024). "Researchers can design corresponding siRNAs to target genes that affect the proliferation and differentiation of tumor cells, such as epidermal growth factor receptor, caspase-3, and caspase-9." (PMID 38429828, 2024). "It was found that FKC treatment suppressed tumor volume and weight and inhibited glycolysis and angiogenesis-related protein expression and phosphorylation of the EGFR/PI3K/Akt/mTOR pathway, whereas knockdown of HSP90B1 strengthened the effect of FKC." (PMID 38711062, 2024). "In a NOD scid γ (NSG) Nalm6 EGFR+ tumor mouse model, PBMCs transduced with MinoCAR showed significanttumor burden control, comparable to the conventional aEGFR CAR." (PMID 38243811, 2024). "CMTM3 is a neoplasm inhibitory gene that inhibits the tumorigenicity of GC cells mediated by epidermal growth factor receptor (EGFR) by increasing the activity of Rab5." (PMID 38536020, 2024). "The involvement of the epithelial growth factor receptor (EGFR) signaling pathway in CRC progression makes EGFR a valuable therapeutic target in developing tumor-targeted therapeutic drugs." (PMID 39136000, 2024). "It suppresses tumor growth by interfering with ligand–receptor interactions and blocking ligand-induced phosphorylation of EGFR and c-MET." (PMID 38892105, 2024). "Our data demonstrated that this combination significantly reduced tumor growth in this EGFR TKI resistant EGFR mutant MET amplified model." (PMID 38485737, 2024). "Cetuximab and nimotuzumab are both EGFR antibodies that inhibit tumor cell growth, angiogenesis, and apoptosis." (PMID 39314629, 2024). "The epidermal growth factor receptor (EGFR) is critical in NSCLC due to its central role in driving tumor progression and proliferation." (PMID 39457585, 2024). "A phase II clinical trial explored the tumor inhibition effect of the combination treatment of DHA with icotinib in EGFR-positive NSCLC patients (NCT03402464)." (PMID 39090653, 2024).
tumor (continued). "Research shows that RT and EGFR TKIs affect extracellular ATP, which can enhance macrophage pro-inflammatory behavior and tumor antigen presentation." (PMID 39772073, 2024). "Regarding tumor grades, EGFR was overexpressed in grades 1 and 2, with a statistically significant difference observed between grade 2 and grade 3." (PMID 39594688, 2024). "It is clear that Tarceva effectively inhibited tumor metastasis to the lungs and reduced the expression of phosphorylated EGFR (pEGFR) in tumors." (PMID 39273055, 2024). "Basal-like/triple negative tumours show low expression or lack hormone receptors and HER2, and some patients/tumours express higher levels of proliferation-related genes and basal markers like keratins 5, 6, 14, 17 and epidermal growth factor receptor (EGFR)." (PMID 38316810, 2024). "The KDM3A/KLF5/SMAD4/EGFR axis coordinates the regulatory mechanism involved in maintaining a low population of T cells within the tumor microenvironment (TME), thus driving resistance to immunotherapies." (PMID 39519018, 2024). "This activation is critical for NSCLC cellular survival, whereas blocking EGFR activity can deeply suppress tumor proliferation." (PMID 39062533, 2024). "A meta-analysis reported primary tumor control and OS in 16 single-arm studies where patients received EGFR TKIs concurrent with thoracic RT or chemoradiation therapy." (PMID 39148905, 2024). "This work established that PDZK1 plays a tumour-suppressing role in TNBC by inhibiting EGFR signalling." (PMID 38604999, 2024). "Several patients experienced grade ≥ 3 adverse effects, including pleural effusion and pulmonary interstitial exudation toxicities, a possible side effect of EGFR-directed on-target/off-tumor responses." (PMID 38650005, 2024). "The predictive efficacy of ctDNA varies according to the mutation type (e.g., EGFR, ALK), tumor stage, and histological subtype distribution." (PMID 39001401, 2024). "The proposed mechanism involved effects on the EGFR signaling pathway and reduction of Nrf2 and p62 expression, genes reported to significantly correlate with tumor aggressiveness, lymph node metastasis, and 5-year survival rate." (PMID 38339275, 2024). "A subgroup analysis of the pTNM and PAULA subsets revealed further alterations: EGFR pathway activity increased with tumor stage (mirrored by EGFR expression)." (PMID 38802361, 2024). "Firstly, previous studies reported that regrafenib targets multiple tumor pathways involved in biliary tumorigenesis, including EGFR, RAS, RAF, VEGFR, FGFR, and PDGFR signaling pathways." (PMID 39359732, 2024). "Researchers at our cancer center are investigating how the ratio of these two tumor components and EGFR-TKI efficacy are related." (PMID 39026979, 2024). "EGFR amplification leads to increased receptor expression and activation, promoting cell proliferation, survival, and tumor invasiveness." (PMID 39767571, 2024). "It was observed that in normal epithelium, JNK acts as a tumor suppressor, and that in tumors with hyperactive Ras-signaling, EGFR activation leads to a change in JNK functioning through Ras-mediated switching, inducing tumor growth in Drosophila." (PMID 39062063, 2024). "A potential limitation of using EGFR-targeted CAR T cells is on-target, off-tumor effects as EGFR is more widely expressed throughout the body than the more specific EGFVIII and thus a higher chance of CAR T associated toxicities ensues." (PMID 39364321, 2024). "In tumors with EGFR or KRAS mutation, IK-930, in combination with EGFR or MEK inhibitors, enhanced cell apoptosis and anti-tumor activity in vivo." (PMID 38499647, 2024). "We highlight the tumor promoting effects of tobacco smoke as it relates to EGFR/MAPK signaling, cell migration and invasion, cell proliferation, immune response, programmed cell death and autophagy." (PMID 38245882, 2024).